NUS1 (NUS1 dehydrodolichyl diphosphate synthase subunit)
Description:
With DHDDS, forms the dehydrodolichyl diphosphate synthase (DDS) complex, an essential component of the dolichol monophosphate (Dol-P) biosynthetic machinery. Both subunits contribute to enzymatic activity, i.e. condensation of multiple copies of isopentenyl pyrophosphate (IPP) to farnesyl pyrophosphate (FPP) to produce dehydrodolichyl diphosphate (Dedol-PP), a precursor of dolichol phosphate which is utilized as a sugar carrier in protein glycosylation in the endoplasmic reticulum (ER). Synthesizes long-chain polyprenols, mostly of C95 and C100 chain length. Regulates the glycosylation and stability of nascent NPC2, thereby promoting trafficking of LDL-derived cholesterol. Acts as a specific receptor for the N-terminus of Nogo-B, a neural and cardiovascular regulator.
Synonyms: NgBR; C6orf68; MGC7199; TANGO14; CDG1AA; MGC:7199; MRD55
Tractability: Small molecule: a structure with a bound ligand is known. Antibody: UniProt predicts a signal peptide or a membrane-spanning region; the Human Protein Atlas places it where antibodies can reach. PROTAC: ubiquitination databases record sites on it.
Gene: Protein-coding gene on chromosome 6 (117,675,469 to 117,710,727, forward strand). Ensembl gene ENSG00000153989.
Subcellular location: Endoplasmic reticulum membrane
Subcellular location (Human Protein Atlas): Vesicles; Plasma membrane
Pathways (Reactome):
Disease: Defective DHDDS causes RP59
Metabolism of proteins: Synthesis of dolichyl-phosphate
Gene Ontology:
Molecular function: ditrans,polycis-polyprenyl diphosphate synthase [(2E,6E)-farnesyl diphosphate specific] activity; prenyltransferase activity; protein binding; transferase activity, transferring alkyl or aryl (other than methyl) groups
Biological process: dolichyl diphosphate biosynthetic process; dolichyl monophosphate biosynthetic process; positive regulation of blood vessel endothelial cell proliferation involved in sprouting angiogenesis; positive regulation of cell migration involved in sprouting angiogenesis; regulation of intracellular cholesterol transport; vascular endothelial growth factor signaling pathway; glycoprotein biosynthetic process
Cellular component: dehydrodolichyl diphosphate synthase complex; endoplasmic reticulum membrane; membrane
Genetic constraint (gnomAD): Loss-of-function variants: 0 observed, 16.42 expected, observed/expected ratio (o/e) 0, 90% interval 0 to 0.18. The upper end of that interval is the gene's LOEUF score, 0.18, which puts it in group 1 of 6, group 1 being the genes least tolerant of losing a copy. Missense variants: 217 observed, 262.98 expected, observed/expected ratio (o/e) 0.83, 90% interval 0.74 to 0.92. Synonymous variants: 112 observed, 105.45 expected, observed/expected ratio (o/e) 1.06, 90% interval 0.91 to 1.24.
Gene-disease validity (ClinGen):
ClinGen rates the evidence that NUS1 causes each of these diseases.
progressive myoclonus epilepsy (autosomal dominant): Definitive. A rare group of disorders characterized by the development of myoclonic and tonic-clonic epileptic seizures associated with progressive degeneration of the nervous system.
Homologues: Orthologues: chimpanzee NUS1 (99% identical), macaque NUS1 (99% identical), pig NUS1 (95% identical), rabbit NUS1 (94% identical), dog NUS1 (92% identical), mouse Nus1 (90% identical), rat Nus1 (89% identical), guinea pig NUS1 (77% identical), zebrafish nus1 (55% identical), tropical clawed frog nus1 (53% identical), Drosophila melanogaster Tango14 (25% identical), Caenorhabditis elegans F37B12.3 (19% identical).